GLP1R (glucagon like peptide 1 receptor)
Diseases named in the same sentence as GLP1R in open-access papers (continued):
Sharing a sentence is not in itself a finding about the gene and the disease.
pancreatitis (48 papers, 2010 to 2026). Inflammation of the pancreas. "In addition, compared with modern western medicine, such as GLP-1R agonists have the risk of nausea, diarrhea, vomiting, constipation and pancreatitis, while XMT has the characteristics of multi-component, multi-target and less adverse reactions." (PMID 40271065, 2025). "Using Glucagon-like peptide-1 receptor agonist (GLP-1RA) increases the risk of pancreatitis and PC." (PMID 39057671, 2024). "While some association exists between the occurrence of pancreatitis and dipeptidyl peptidase 4 inhibitors (DPP4i) and glucagon-like peptide-1 receptor agonists (GLP-1RA), there are only a few reports linking sodium-glucose co-transporter-2 inhibitors (SGLT-2is) with pancreatitis." (PMID 39036218, 2024). "Dipeptidylpeptidase-4 (DPP4) inhibitors and Glucagon-like peptide-1 receptor agonist (GLP-1RAs) are important treatments for T2D.These medicines may increase the risk of pancreatitis." (PMID 37467250, 2023). "Incretin-based therapies (glucagon-like peptide-1 receptor agonists and oral dipeptidyl peptidase-4 inhibitors) are avoided because of concerns about pancreatitis." (PMID 40401174, 2025). "Despite clear advantages to GLP-1R agonist use in lipodystrophy presented here, some patients with lipodystrophy also develop pancreatitis." (PMID 38745956, 2024). "As a result, it is recommended to monitor pancreatic function when treating AUD patients or to avoid GLP-1R agonists altogether in those with pancreatitis." (PMID 37063267, 2023). "A recent systematic review of case reports of adverse events linked to GLP-1R agonists highlighted cases of pancreatitis associated with liraglutide and exenatide, although none with semaglutide." (PMID 38745956, 2024). "Although an efficient drug class for the treatment of T2D, recent data indicate that long-term administration of the GLP-1R agonists and DPP4 inhibitors may be linked to an increased risk of pancreatitis and pancreatic cancer." (PMID 25119717, 2014). "In addition, GLP-1R agonists have been linked to an increased risk of pancreatitis, which could be problematic for AUD patients, as some of them may already have pancreatitis." (PMID 37063267, 2023). "On the other hand, previous studies have shown that genetic and pharmacological interference with GLP-1R does not affect the severity of pancreatitis in cerulein model of this disease." (PMID 26226277, 2015). "However, while GLP-1 receptor (GLP-1R) agonistic agents are effective medicines for T2DM, some unavoidable side effects include nausea, vomit, autoimmune hepatitis, acute kidney injury, pancreatitis, and pancreatic cancer." (PMID 30298009, 2018).
type 1 diabetes (47 papers, 2011 to 2026). "The role of glucagon-like peptide-1 receptor agonists in type 1 diabetes has been investigated using exenatide and liraglutide, which have been reported to reduce insulin requirements, promote weight loss, and improve HbA1c levels." (PMID 40429740, 2025). "It has been previously demonstrated that liraglutide, a glucagon-like peptide-1 receptor agonist, restores β-cell mass in type 1 diabetes, via α-cell transdifferentiation and neogenesis." (PMID 33144616, 2020). "We sought to investigate the real-world impact of sodium–glucose cotransporter 2 inhibitor (SGLT2i) and glucagon-like peptide-1 receptor agonist (GLP-1 RA) therapy in individuals with type 1 diabetes in relation to effect on blood glucose levels, adverse events and cardio-renal outcomes." (PMID 37505282, 2023). "Therefore, increased BER levels seem to be associated with the plasma glucose-lowering effect of liraglutide via the activation of GLP-1R in rats with type-1 diabetes." (PMID 33233692, 2020). "The role of the autonomic nervous system in the efficacy of glucagon-like peptide-1 receptor agonists (GLP-1 RA) in patients with type 1 diabetes is unknown." (PMID 31031712, 2019). "Long-term assessment of treatment effects on DCAN could be important during therapy with glucagon-like peptide 1 receptor agonists, which improve glucose metabolic parameters in type-1 diabetes (Guyton, Jeon and Brooks, 2019) but might exacerbate DCAN impairing the HRV vagal indexes." (PMID 35846022, 2022). "In fact, although cytoprotective properties on renal tissue derived from the amelioration of insulin cannot be excluded, the results obtained in type 1 diabetes models suggest extra-pancreatic (renoprotective) effects of GLP-1/GLP-1R." (PMID 24817793, 2014). "In contrast, much less is known about whether the actions of GLP-1R agonists are maintained in the setting of an ongoing autoimmune attack, as is the case in the NOD mouse, the BB rat, and in human subjects with type 1 diabetes (T1D)." (PMID 21716694, 2011). "Oral medications serve as the cornerstone for treating T2DM, whereas injectable options, including insulin and glucagon-like peptide-1 receptor agonists (GLP-1 RAs), are implemented for both type 1 diabetes mellitus (T1DM) and more advanced stages of T2DM." (PMID 40648562, 2025).
depression (43 papers, 2019 to 2026). "The data indicated that activation of GLP-1R alleviated depression-like behaviors and associated neuroinflammation through inhibiting GSDMD-mediated microglial pyroptosis by promoting mitophagy in the depressive hippocampus." (PMID 36615696, 2022). "First, GLP1R agonists have been associated with the over-activation of GSK3β (glycogen synthase kinase-3β) in a depression model of chronic corticosterone (CORT) administration in mice, suggesting a potential link between GLP1R signaling and GSK3β-related pathways." (PMID 40770700, 2025). "Although few studies have shown that GLP-1R agonists may be valuable in the treatment of depression, the exact causal relationship and mechanism of the antidepressant and anti-diabetic effects of GLP-1 agonists have not been elucidated." (PMID 36615696, 2022). "Thus, we aim to evaluate whether GLP-1R agonist exendin-4 (EX-4) could alleviate depression-like behaviors in diabetic mice and to explore its underlying mechanism." (PMID 36615696, 2022). "Second, GLP1R agonists promoted adult neurogenesis in the dentate gyrus of the hippocampus, a process known to be reduced in both animal models of depression and human patients." (PMID 40770700, 2025). "A recent large community-based cohort study including over 160 000 patients in each group found that women show a hazard ratio of 3.16, compared to males at 2.89, of being diagnosed with depression after GLP-1R analog therapy." (PMID 39715341, 2025). "The slight increase in reports of depression, hallucinations, or confusion in the GLP-1R agonist group is an unexpected finding that requires further investigation." (PMID 39201039, 2024). "In the present study, we demonstrated for the first time that activation of GLP-1R significantly ameliorated depression-like behaviors in diabetic db/db mice by inhibiting microglial pyroptosis and promoting mitophagy in the hippocampus." (PMID 36615696, 2022). "Our findings support previous studies on the role of microglial pyroptosis in depression psychopathology in order to identify their importance in the antidepressant effect of activation of GLP-1R." (PMID 36615696, 2022). "To determine the distribution of GLP-1R in the brain, we first examined the expression of GLP-1R in the hippocampus, amygdala, and anterior cingulate cortex (ACC), which are strongly associated with depression." (PMID 36615696, 2022). "Treatment with GLP-1R agonist EX-4 markedly ameliorated the depression-like behavior in db/db mice, suggesting that GLP-1R is involved in the depression modulation in diabetic mice." (PMID 36615696, 2022). "In our studies conducted in a prenatal stress model (PS) of depression in rats, adult PS animals showed a significant decrease in GLP-1R protein levels in the hippocampus after the acute immobility stress." (PMID 34003475, 2021). "By influencing neurotransmitter systems, GLP-1R agonists might ameliorate depression, anxiety and motivational deficits commonly observed in these conditions." (PMID 41226780, 2025). "Clinical trials have reported improvements in depression rating scales among GLP1R agonist users." (PMID 40770700, 2025). "For the treatment of many diseases, such as weight rebound, gastrointestinal adverse reactions, thyroid cancer, suicidal depression tendencies etc., GLP‐1R is an excellent drug target, but its side effects may raise concerns." (PMID 40277442, 2025). "Finally, through primary and in-depth silico analyses, we demonstrated multiple findings supporting that GLP1R agonists can induce depression phenotypes." (PMID 39865816, 2025). "In addition, rats overexpressing GLP-1R showed improved learning and memory, whereas GLP-1 deficiency due to REM sleep deprivation can negatively impact anxiety and depression behaviors." (PMID 39329893, 2024).
depression (continued). "Glucagon-like peptide-1 receptor (GLP-1R) is an incretin hormone that has been shown to improve memory deficits in a variety of diseases, including bipolar disorder, diabetes-related depression and cognitive impairment, and depression." (PMID 39257395, 2024). "The GLP-1R rs1042044 gene polymorphism has been genetically linked to anhedonia but not to major depression diagnoses; unfortunately, no such data exist for psychotic disorders." (PMID 36979648, 2023). "In this study, GLP-1R was expressed in all these three depression-related regions but only highly expressed in the hippocampus, suggesting GLP-1R in the hippocampus may play a crucial role." (PMID 36615696, 2022). "It is also noteworthy that central GLP-1R signaling appears to be impaired in chronic stress conditions or under the influence of a high concentration of glucocorticoids, often observed in patients with depression." (PMID 34003475, 2021). "Thus, further studies are needed to better elucidate the effects of different GLP-1R agonists on anti-inflammatory actions in depression." (PMID 34003475, 2021). "Besides, this study validated that [18F]DPA-714 and [18F]exendin-4 PET have the potential for noninvasive evaluation of microglial activation and GLP-1R expression in the brain of depression." (PMID 33414373, 2021). "What is more, it seems that GLP-1R agonists may be useful as an adjunctive to traditional therapy to treat cognitive impairments observed in the course of depression, especially in women." (PMID 34003475, 2021). "Considering the relationship between GLP-1 signaling and behavioral symptoms characteristic of depression, it was shown that intracerebroventricular (icv) administration of both GLP-1 and exendin-4 enhances associative and spatial learning, while these effects are inhibited by a GLP-1R antagonist." (PMID 34003475, 2021). "Moreover, GLP-1RAs have cognition-promoting effects and activate the GLP-1R/cAMP/PKA pathway, thus providing a new intervention for the treatment of depression and reduction of SSIBs." (PMID 38355513, 2024). "In a chronic unpredictable mild stress (CUMS) depression mouse model, Clostridium butyricum was found to attenuate depressive-like behavior by increasing 5-HT, Glucagon-like peptide-1 (GLP-1), and Glucagon-like peptide 1 receptor (GLP-1R) concentrations and upregulating BDNF expression." (PMID 37759312, 2023). "A 2023 meta-analysis (5 trials, 1 cohort study, >2000 participants) revealed that glucagon-like-peptide-1 receptor agonists (GLP-1RAs) such as liraglutide and semaglutide produced moderate reductions in depression scores versus control treatments, independent of weight loss." (PMID 41373485, 2025).
steatosis (42 papers, 2014 to 2026). Increased lipid within the cytoplasm of cells. "Nonetheless, the precise mechanisms underlying the observed protective effect of GLP-1R agonists on steatosis remain to be unraveled." (PMID 40002783, 2025). "Here, we sought to identify the long non-coding RNAs (LncRNAs) associated with the steatosis improvement induced by the GLP-1R agonist Exendin-4 (Ex-4) in vitro." (PMID 34078383, 2021). "An investigation demonstrated that both live and heat-inactivated Butyricimonas virosa mitigated adverse effects such as weight loss, hyperglycemia, and steatosis—in diseased mice by activating Glucagon-like peptide 1 receptors (GLP-1R) in the liver within an obese mouse model." (PMID 38988982, 2024). "Our results suggest that LncRNAs may play essential roles in the mechanisms underlying steatosis improvement in response to GLP-1R agonists and warrant further functional studies." (PMID 34078383, 2021). "The reduction in steatosis in the GLP-1R agonist-treated group was accompanied by suppressed expression of hepatic genes for de novo lipogenesis (Acc1, Srebp1c and Fasn), for reactive oxygen stress (Nrf2, Nox2) and inflammation (Mpo, Il-6, Il-12)." (PMID 40968135, 2025). "Recently, we proposed that the direct activation of GLP-1R by Ex-4 mitigates steatosis induced by oleic acid (OA) in HepG2 cells." (PMID 40002783, 2025). "Our study suggests that GLP-1R agonists improve insulin sensitivity, glycaemic control, steatosis, and pancreatic beta cell function in CGL and, likely, in lipodystrophies more broadly." (PMID 38745956, 2024). "This study concluded that the direct activation of GLP-1R by exendin-4 reduces steatosis in an in vitro model via stimulation of the Wnt/β-catenin signaling pathway and reduces FOXA1 expression and FABP1 expression, resulting in decreased FFA uptake." (PMID 37367037, 2023). "Functional analyses are needed to validate the present observations and better define the role of the DEmiRs in the development of steatosis and the positive effect of GLP-1R agonists on NAFLD." (PMID 37511368, 2023). "Given that NAFLD is a metabolic disease, understanding how GLP-1R agonists impact the structure of biomolecules, such as proteins, lipids, and carbohydrates, could provide valuable insights into the mechanisms underlying the protective effect of these agents on steatosis and NAFLD." (PMID 36289914, 2022). "Our findings suggest that direct activation of GLP-1R by Ex-4 reduces OA-induced steatosis in HepG2 cells by reducing fatty acid uptake and transport via FABP1 downregulation." (PMID 35140289, 2022). "Liraglutide is a glucagon-like peptide 1 receptor (GLP-1R) agonist that can effectively control blood glucose and improve metabolism, and it has a significant effect on reducing liver inflammation, steatosis, and fibrosis." (PMID 35958576, 2022). "We aimed to investigate these mechanisms using an in vitro model of steatosis treated with the GLP-1R agonist Exendin-4 (Ex-4)." (PMID 35140289, 2022). "In conclusion, the present study proposes that the direct activation of GLP-1R by Ex-4 reduces OA-induced steatosis in HepG2 cells by stimulating the Wnt/β-catenin signaling pathway, which reduces FOXA1 expression." (PMID 35140289, 2022). "To overcome this challenge, we opted for the in vitro model to ascertain that Ex-4's effect on steatosis results from direct activation of the GLP-1R." (PMID 35140289, 2022). "We acknowledge the limitations of using the HepG2 as an in vitro steatosis model to investigate an important question such as the mechanisms involved in the protective effect of the GLP-1R agonists." (PMID 34078383, 2021). "We opted for an in vitro model of steatosis to overcome the pleiotropic effects that characterize the action of GLP-1R agonists in vivo." (PMID 34078383, 2021). "Further studies are warranted to unravel how all these signaling pathways' combined effect leads to improvement of steatosis upon treatment with GLP-1R agonists." (PMID 34078383, 2021).
steatosis (continued). "A Spearman correlation analysis confirmed that the pathological index of steatosis was negatively correlated with the hepatic GLP-1R expression level." (PMID 30510243, 2018). "However, no sufficient data are available about the potential benefits of GLP-1R agonists on the regression of fibrosis and the prevention of the progression of steatosis to MASH and cirrhosis." (PMID 40869400, 2025). "Our findings suggest that miRNAs may play essential roles in the processes driving steatosis reduction in response to GLP-1R agonists, which warrants further functional investigation." (PMID 37511368, 2023). "Recently, we and others have shown that the GLP-1R agonist Exendin-4 (Ex-4) reduces the fat content in an in vitro cell model of steatosis by inhibiting hepatic lipogenesis through activation of β-catenin signaling and modulation of the expression of several lipogenesis genes." (PMID 36289914, 2022). "A more in-depth understanding of the pathways through which GLP-1R agonists may alleviate steatosis is critical for clinical development as it may open new avenues for developing newer, safer, and more potent medications." (PMID 36289914, 2022). "We employed transcriptomics and functional pathway analysis to show that the Ex-4-induced steatosis improvement in HepG2 cells might be partially explained by activation of the FXR/RXR activation pathway via direct stimulation of the GLP-1R." (PMID 35625757, 2022). "GCGR/GLP-1R dual agonism is also a focus in the treatment of NASH as it can potentially ameliorate hepatic fat accumulation, steatosis and fibrosis, alongside reductions in bodyweight." (PMID 38095657, 2024). "Combined treatment with GLP-1R and GIPR agonists improved NASH steatosis, lobular inflammation, hepatocyte ballooning, and fibrosis." (PMID 35773269, 2022). "Research utilising primary human hepatocytes and hepatic stellate cells often demonstrates negligible or absent GLP‐1R signalling, along with no direct diminution in steatosis or fibrogenic indicators under regulated conditions." (PMID 41545323, 2026). "Using Fourier transform infrared (FTIR) spectroscopy, we sought to investigate the biochemical changes in a steatosis cell model treated or not with the GLP-1R agonist Exendin-4 (Ex-4)." (PMID 36289914, 2022). "While the role of LncRNAs in the protective effect of GLP-1R agonists in steatosis has not been researched in vivo, there is ample evidence that these drugs do reduce fat liver content both in NAFLD patients and animal models." (PMID 34078383, 2021). "Moreover, as described in the previous section, it is uncertain whether the decrease in steatosis seen in animal and human studies after treatment with GLP-1RAs is a result of the direct activation of hepatic GLP-1R or an indirect effect." (PMID 37367037, 2023). "In agreement, GLP1R agonists have been reported to reduce hepatocarcinogenesis in non-obese chemical carcinogen-induced mouse models of HCC, perhaps by limiting liver pro-tumorigenic metabolic factors such as hepatic insulin resistance, steatosis and inflammation." (PMID 38155202, 2023). "Furthermore, while activation of the LXR/RXR activation pathway by Ex-4 in our model does not reconcile with steatosis reduction in in vivo studies, GLP-1R agonists may employ this pathway to reduce hepatic inflammation and so alleviate NAFLD." (PMID 35625757, 2022). "Furthermore, microvascular steatosis was lower upon GLP1R agonism, but not GIPR agonism, while combined GIPR/GLP1R agonism led to a pronounced reduction in microvascular steatosis even when compared to single GIPR and GLP1R agonism." (PMID 37379656, 2023).